Y_RNA (Y RNA )
Gene: Miscellaneous RNA gene on chromosome 3 (177,120,691 to 177,120,800, reverse strand). Ensembl gene ENSG00000201343.
Homologues: Orthologues: chimpanzee Y_RNA (98% identical), guinea pig Y_RNA (85% identical), macaque Y_RNA (85% identical), guinea pig Y_RNA (84% identical), guinea pig Y_RNA (82% identical). Paralogues in human: RNY1 (82% identical), Y_RNA (82% identical), Y_RNA (79% identical), RNY1P11 (78% identical), RNY1P5 (78% identical), Y_RNA (78% identical), RNY1P8 (77% identical), Y_RNA (77% identical), Y_RNA (76% identical), RNY1P7 (75% identical), Y_RNA (75% identical), RNY1P10 (75% identical), and 91 more.